H2BC15 (H2B clustered histone 15)
Description:
Core component of nucleosome. Nucleosomes wrap and compact DNA into chromatin, limiting DNA accessibility to the cellular machineries which require DNA as a template. Histones thereby play a central role in transcription regulation, DNA repair, DNA replication and chromosomal stability. DNA accessibility is regulated via a complex set of post-translational modifications of histones, also called histone code, and nucleosome remodeling.
Synonyms: H2B/d; H2BFD; HIST1H2BN
Tractability: PROTAC: UniProt records ubiquitination sites on it; ubiquitination databases record sites on it.
Gene: Protein-coding gene on chromosome 6 (27,838,545 to 27,855,709, forward strand). Ensembl gene ENSG00000233822.
Subcellular location: Nucleus; Chromosome
Subcellular location (Human Protein Atlas): Nucleoplasm; Cytosol
Pathways (Reactome):
Gene expression (Transcription): B-WICH complex positively regulates rRNA expression; DNA methylation; ERCC6 (CSB) and EHMT2 (G9a) positively regulate rRNA expression; MLL4 and MLL3 complexes regulate expression of PPARG target genes in adipogenesis and hepatic steatosis; NoRC negatively regulates rRNA expression; PRC2 methylates histones and DNA; RNA Polymerase I Promoter Escape; RNA Polymerase I Promoter Opening; RUNX1 regulates genes involved in megakaryocyte differentiation and platelet function; RUNX1 regulates transcription of genes involved in differentiation of HSCs; Regulation of endogenous retroelements by KRAB-ZFP proteins; Regulation of endogenous retroelements by Piwi-interacting RNAs (piRNAs); Regulation of endogenous retroelements by the Human Silencing Hub (HUSH) complex; SIRT1 negatively regulates rRNA expression; Transcriptional regulation by small RNAs
Chromatin organization: CHD1 and CHD2 subfamily; CHD6, CHD7, CHD8, CHD9 subfamily; ChAHP complex assembly; HATs acetylate histones; HDACs deacetylate histones; Interaction of NuRD complexes with transcription factors; NuRD complex assembly
DNA Repair: Cleavage of the damaged purine; Cleavage of the damaged pyrimidine; Nonhomologous End-Joining (NHEJ); Processing of DNA double-strand break ends; Recognition and association of DNA glycosylase with site containing an affected purine; Recognition and association of DNA glycosylase with site containing an affected pyrimidine; Recruitment and ATM-mediated phosphorylation of repair and signaling proteins at DNA double strand breaks
Cell Cycle: Condensation of Prophase Chromosomes; Deposition of new CENPA-containing nucleosomes at the centromere; G2/M DNA damage checkpoint; Inhibition of DNA recombination at telomere; Packaging Of Telomere Ends
Disease: Defective pyroptosis; Dengue Virus-Host Interactions; HCMV Early Events; HCMV Late Events; RSV-host interactions
Developmental Biology: Activation of anterior HOX genes in hindbrain development during early embryogenesis
and 19 more pathways
Gene Ontology:
Molecular function: DNA binding; structural constituent of chromatin; protein heterodimerization activity
Biological process: antibacterial humoral response; antimicrobial humoral immune response mediated by antimicrobial peptide; chromatin organization; innate immune response in mucosa; nucleosome assembly
Cellular component: extracellular exosome; nucleus; nucleoplasm; nucleosome; chromosome
Genetic constraint (gnomAD): Loss-of-function variants: 5 observed, 6.73 expected, observed/expected ratio (o/e) 0.74, 90% interval 0.39 to 1.53. That is too few expected variants to judge how well the gene tolerates losing a copy. Missense variants: 148 observed, 178.62 expected, observed/expected ratio (o/e) 0.83, 90% interval 0.72 to 0.95. Synonymous variants: 87 observed, 80.63 expected, observed/expected ratio (o/e) 1.08, 90% interval 0.91 to 1.29.
Homologues: Orthologues: chimpanzee H2BC15 (100% identical), macaque H2BC15 (100% identical), mouse H2bc3 (98% identical). Paralogues in human: H2BC10 (99% identical), H2BC4 (99% identical), H2BC5 (99% identical), H2BC6 (99% identical), H2BC7 (99% identical), H2BC8 (99% identical), H2BC12 (98% identical), H2BC21 (98% identical), H2BC3 (98% identical), H2BC9 (98% identical), H2BC11 (98% identical), H2BC13 (98% identical), and 9 more.
Diseases named in the same sentence as H2BC15 in open-access papers:
H2BC15 is named in the same sentence as 10 diseases in open-access papers, as found by Europe PMC text mining. Sharing a sentence is not in itself a finding about the gene and the disease. The quoted sentences say what the papers report.
prostate carcinoma (1 paper, 2023). A carcinoma that arises from epithelial cells of the prostate gland. "In addition, we explored therapeutic targets by investigating FOXA1 interacting protein within proteins encoded by upregulated genes in FOXA1 mutant prostate cancer, and identified six genes—HSP90AB1, KDM1A, FKBP4, H2BC15, WNT7B, and GRB7." (PMID 37958805, 2023).
H2BC15 also shares sentences with these, for which no sentence is quoted: meningioma (2 papers); autism spectrum disorder (1); bipolar disorder (1); cancer (1); depression (1); heart failure (1); psychiatric disorder (1); schizophrenia (1); systemic lupus erythematosus (1).